IFNG (interferon gamma)
Diseases named in the same sentence as IFNG in open-access papers (continued):
Sharing a sentence is not in itself a finding about the gene and the disease.
chronic hepatitis B (43 papers, 2009 to 2025). "Our patients with MDhi CD4 TEM and memory CD8 T cells exhibited functional exhaustion with reduced production of pro-inflammatory cytokines such as TNFα and IFNγ, which was also in line with other reports on chronic hepatitis B or long-term tumor antigen exposure." (PMID 35095881, 2021). "Whether the impaired DC-NK cell crosstalk could explain the defective IFNγ production by NK cells circulating in patients with chronic hepatitis B remains unknown." (PMID 21246041, 2011). "Indeed, improving mitochondrial function by the anti-oxidant piperidine-nitroxide MitoTempo and IL-12 increased IFNγ release upon stimulation with HIV gag as well as CMV pp65, but did not affect the percentage of IFNγ, TNFα and IL-2 producing CD8 T cells as was observed in chronic hepatitis B." (PMID 39356699, 2024). "In contrast to previous observations in chronic hepatitis B, in PWH the percentage of IFNγ, TNFα and IL-2 producing CD8 T cells did not increase in the presence of MitoTempo and IL-12." (PMID 39356699, 2024).
lupus nephritis (43 papers, 2008 to 2025). Glomerulonephritis in the context of systemic lupus erythematosus. "IFNγ has been reported to play a pathogenic role in lupus nephritis." (PMID 28982388, 2017). "The loss of the mitigation effect on renal inflammation in EGR2-/-B6/lpr mice is likely due to enhanced IFNγ production, another key inflammatory cytokine driving renal inflammation and lupus nephritis in lpr mice." (PMID 35784356, 2022). "Richardset al.12 showed that IFNγ is an important component in the development of lupus nephritis in pristane-induced murine models." (PMID 34386197, 2020). "Our results indicated that the participation of Klotho in lupus nephritis may be partially attributed to its inhibitory effect on IFNγ-induced SAMHD1 expression and NFκB activation in MES-13 cells." (PMID 37213666, 2023). "Induction with pristane in an IFNγ deficient mouse (IFNγ-/-) would not result in a change of renal pathology corresponding to lupus nephritis." (PMID 34386197, 2020). "Reduction of IFNγ levels could improve the outcome of lupus nephritis by inactivating B7/CD28 signalling pathway, which results in a reduction in ANA autoantibodies, IL-4 and IFNγ levels." (PMID 34386197, 2020). "In lupus nephritis, interferon gamma and interleukin 17 are elevated, potentially indicating that Th1 and Th17 cells may play a role in the severity of lupus nephritis." (PMID 25133068, 2014). "The present study verified the effect of IFNγ on SAMHD1 and Klotho expression in MES-13 glomerular mesangial cells, a special cell type in glomerulus that is critically involved in lupus nephritis." (PMID 37213666, 2023). "Collectively, our findings support the protective role of Klotho in attenuating lupus nephritis through the inhibition of IFNγ-induced SAMHD1 expression and IFNγ downstream signaling in MES-13 cells." (PMID 37213666, 2023). "The increased activity of Th1 and reduced activity of Treg, in this study represented by pro-inflammatory IFNγ levels and FOXP3 mRNA expression, has proven to be related to the development of lupus nephritis." (PMID 34386197, 2020). "Coincidently, neither IL-10+/− nor IFNγ+/− MRL/lpr had altered autoantibody titers, while the loss of one allele resulted in worsened or attenuated lupus nephritis, respectively." (PMID 31311609, 2019). "In MRL/lpr mice that had experienced pregnancy and lactation, we found that the effects of vancomycin and L. animalis were mostly on lupus nephritis but not autoantibody production, which coincides with the observation in IFNγ+/− MRL/lpr mice." (PMID 31311609, 2019).
respiratory infections (43 papers, 2010 to 2025). "This mRNA virus causes an inflammatory respiratory infection that mainly affects the lower respiratory tract and is marked by a rise in proinflammatory cytokines like interleukin 6 (IL-6) and interferon-gamma (IFN-γ)." (PMID 37519527, 2023). "The vaccinations that elicited a significant level of protection against weight loss and infectious burden following an respiratory infection, induced secretion of the pro-inflammatory cytokine TNFα, IL-17 and IFNγ by splenocytes following in vitro re-stimulation with MOMP." (PMID 23613984, 2013). "IFNγ is an effector cytokine secreted by T cells and NK cells mediating antiviral function, including in respiratory infections like SARS-CoV-2." (PMID 40498720, 2025). "FeNO levels may increase in patients with acute or chronic airway inflammation, such as type 2 bronchial asthma, and some respiratory infections sustained by viruses through an interferon-gamma (IFNγ)-mediated pathway." (PMID 37947596, 2023). "In addition, serum levels of the antiviral factor interferon-gamma were significantly increased by 40% after 10 days of CU1 supplementation, compared to baseline within the supplementation group, and decreased risk of respiratory infection was observed in a post hoc analysis, compared to placebo." (PMID 37630670, 2023). "Respiratory infection of CARD9−/− mice with C. neoformans results in increased lung fungal burden and neutrophilia along with defective early IFNγ production by NK cells and memory T cells." (PMID 28936464, 2017).
fibrosarcoma (41 papers, 2007 to 2024). A malignant mesenchymal fibroblastic neoplasm affecting the soft tissue and bone. "Several studies focusing on the MHC have also already demonstrated such a phenomenon after up-regulation by IFNγ in cell types other than immune cells, including fibroblasts and fibrosarcoma-type cancer cells." (PMID 34521351, 2021). "The cytostatic activities of IFNγ and TCP-1/IFNγ were determined in a murine fibrosarcoma cell line (L929) and a mouse colonic adenocarcinoma cell line (Colon 26)." (PMID 27342639, 2016). "However, it was shown in a study on promoting IFNγ expression in murine fibrosarcoma and adenocarcinoma cells that that IFNγ directly inhibited angiogenesis and cut off blood flow to bring about intratumoral ischemia, by binding to IFNγ receptors on tECs." (PMID 34476218, 2021). "Preclinical studies with syngeneic mice injected with fibrosarcoma cells engineered to be insensitive to IFNγ demonstrated increased tumorigenicity versus their IFNγ-sensitive counterparts, inferring a role for this molecule in tumor cell immunogenicity, recognition and elimination." (PMID 24213130, 2011). "Studies have shown that immunocompromised mice lacking a functional interferon gamma (IFNγ) system (IFNγ receptor-1/alpha chain-deficient mice) or an intact T cell compartment are more susceptible to carcinogen-induced tumors, such as fibrosarcomas." (PMID 27843441, 2016). "The observation that endogenous interferon gamma (IFN-γ) and also IFN-α/β can contribute to protection against the growth of methylcholanthrene-induced fibrosarcomas implies that IFN signaling plays a key role in the immune protection against murine cancer." (PMID 24829752, 2013). "The present study explored the in vivo immunomodulatory effect on interferon-gamma (IFN-γ), interleukin-17 (IL-17), and transforming growth factor-beta 1 (TGF-β1) evoked by two water-extracts prepared from EJ leaves in the tissues of normal and Meth-A-fibrosarcoma bearing mice." (PMID 21294856, 2011).
pneumococcal infection (41 papers, 2010 to 2025). Infections with bacteria of the species streptococcus pneumoniae. "Genetic deficiency for IFNγ or IFNGR1 or neutralization of IFNγ also improved survival from secondary pneumococcal infection." (PMID 32117259, 2020). "The pneumococcal infection was also associated with a significant increase in the expression of IL-6, TNF-α, CXCL1, and IFNγ in both groups and was significantly higher in the Zip8KO group when compared to the WT animals (p = 0.055)." (PMID 35162945, 2022). "We proposed that STING expression in monocyte/monocyte-derived cells produces IL-12p70 that drove late-stage lung IFNγ production by NK cells and neutrophils during pneumococcal infection." (PMID 34512626, 2021). "The late-stage lung IFNγ in pneumococcal infection, however, may be detrimental because in patients with S. pneumoniae sepsis, IFNγ was elevated and correlated with increased mortality." (PMID 34512626, 2021). "Streptococcus pneumoniae infection induces strong IFNγ production in the lungs." (PMID 34512626, 2021). "The discovery of two waves of lung IFNγ production during S. pneumoniae infection may clarify the role of IFNγ in pneumococcal infection." (PMID 34512626, 2021). "In summary, the activation of the STING pathway in monocyte/monocyte-derived cells can synergize with the MyD88 pathway to drive IFNγ production during pneumococcal infection that may influence the development of adaptive immunity." (PMID 34512626, 2021). "We speculated that the two waves of lung IFNγ may play opposite roles in host defense against pneumococcal infection." (PMID 34512626, 2021).
coronary artery disease (40 papers, 2012 to 2025). "For example, we highlighted the IFNγ-specific eQTL rs10418535 associated with coronary artery disease." (PMID 37805492, 2023). "Given the importance of cytokines in the context of the failing heart, the prevalence of Interleukin-2 (IL-2) and Interferon-gamma (IFN-γ) polymorphisms was studied in patients with CHF due to ischemic heart disease in a case-control study." (PMID 30090212, 2018). "Although IFNγ-KO mice were protected from developing coronary arteriosclerosis, both wild-type (WT) and IFNγ-KO mice given heart transplants developed myocardial rejection." (PMID 41155497, 2025). "Myocardial rejection occurred in both wild-type and IFNγ-KO mice given heart transplants, but the IFNγ-KO mice were protected from developing coronary arteriosclerosis." (PMID 40607379, 2025). "In two studies among patients with coronary artery disease, it reduced the concentrations of pro-inflammatory interleukins (ILs) 8 and 12; interferons, including interferon gamma (IFN-γ); and IL-1β." (PMID 38138886, 2023). "In adult OSA patients, elevated levels of IFNγ were found in the group with concomitant coronary heart disease." (PMID 36769452, 2023). "Moreover, several reports suggest that the cytokine interferon-gamma, which is released during the cell-mediated immune responses that take place in coronary heart diseases, induces IDO-1 activity." (PMID 37616231, 2023). "The inflammatory mediators C-reactive protein and interferon-gamma were found to enhance the expression of macrophage tissue factor levels that may contribute to the hypercoagulable state in coronary disease." (PMID 35268431, 2022). "The aims of the study were to examine the associations of plasma levels of five cytokines (interleukin (IL)-6, IL-5, interferon-gamma (IFN-γ), tumour necrosis factor-alpha (TNF-α) and IL-6 receptor (IL-6R)) and C reactive protein (CRP) with risk of coronary heart disease (CHD)." (PMID 29713486, 2018). "IL-1, interferon gamma (IFN-γ) and tumor necrosis factor alpha (TNF-α) are also important both the development of coronary heart disease and plaque destabilization." (PMID 26100072, 2015). "Proinflammatory cytokines like interleukin-1 (IL-1), interleukin (IL-6), interferon-gamma (IFN-γ) and tumor necrosis factor-α (TNF-α) predict the cardiovascular risks including coronary artery disease, myocardial infarction, chronic heart failure, peripheral arterial disease and unstable angina." (PMID 31491986, 2019). "Our study indeed provides evidence that in ECs and VSMCs STAT1 coordinates a platform for cross-talk between IFNγ and TLR4, and identifies a STAT1-dependent gene signature that reflects a pro-atherogenic state in coronary artery disease (CAD) and carotid atherosclerosis." (PMID 25478796, 2014).
Cryptosporidium infection (40 papers, 2012 to 2025). "In humans, patients that produce insufficient amounts of the cytokine interferon gamma (IFNγ) are documented to be highly susceptible to cryptosporidiosis." (PMID 33312965, 2020). "Similarly, a case of severe cryptosporidiosis was reported in a patient with an IFNγ deficiency and IFNγ gene-knockout mice are highly susceptible to infection." (PMID 28800747, 2017). "In vivo efficacy of BKI-1708 was previously demonstrated in an IFNγ-KO immunocompromised acute mouse model of Cryptosporidium infection with 5 days of once daily (QD) oral doses as low as 8 mg/kg." (PMID 40737275, 2025). "Preliminary experiments demonstrated excellent in vitro activity against CpCDPK1 and C. parvum parasites and potent in vivo efficacy in an IFNγ-KO mouse model of Cryptosporidium infection." (PMID 40737275, 2025). "The role of IFNγ in cryptosporidiosis is well established, but there have also been reports of interferons directly produced by the enterocyte during Cryptosporidium infection." (PMID 35584177, 2022). "Early in Cryptosporidium infection, the main cytokine involved in the coordination of innate and adaptive immune responses is interferon-gamma (IFN-γ), which is secreted by natural killer (NK) cells, dendritic cells, and macrophages." (PMID 36718331, 2022). "Although it has been known for nearly 30 years that IFNγ is a crucial cytokine for resistance to Cryptosporidium, the particular mechanism of this cytokine’s effect on Cryptosporidium infection remains largely a mystery." (PMID 33312965, 2020). "infection is an excellent example of the essential role of IFNγ for the control of cryptosporidiosis." (PMID 29295550, 2017). "Briefly, NK cells are an important source of IFNγ in cryptosporidiosis and they are key players in controlling the infection in mice." (PMID 29295550, 2017). "Cell-mediated responses, especially interferon gamma (IFN-γ) production by CD4+ T cells, are well described in individuals with prior cryptosporidiosis." (PMID 31131855, 2020). "While the mechanisms remains incompletely understood, SP is known to stimulate pro-inflammatory cytokines including interferon gamma (IFN-γ), IL-1β and TNF-α, which are known to contribute to the pathophysiology of cryptosporidiosis." (PMID 26635531, 2015). "The production of interferon gamma (IFNγ) is recognized to be one of the essential functions of T cells during Cryptosporidium infection, but T cells are not the only source of IFNγ." (PMID 35584177, 2022). "Despite intensive investigations, the cells producing IFNγ in the intestinal mucosa during neonatal cryptosporidiosis have not been identified." (PMID 24367259, 2013). "Significant gaps remain in our understanding of the cellular source of IL-18 during Cryptosporidium infection and its ability to promote innate production of IFNγ and whether it is required for tissue repair independent of IFNγ." (PMID 33372132, 2021). "Consequently, like in malnourished children with active cryptosporidiosis, either peak primary C. parvum challenge during PM in mice or stimulation of their naïve lymphocytes with C. parvum antigens elicits a basal IL13 response rather than IFNγ." (PMID 27467505, 2016).
hepatitis C (40 papers, 2010 to 2025). "Polymorphism of IFNG was shown to have a role in recurrent hepatitis C after transplantation." (PMID 29531550, 2017). "Single-cell RNA-seq analysis confirmed the impact of type I IFN on fibrosis progression, showing reduced expression of viral protein interaction genes (Ccl12, Xcr1) and hepatitis C-related genes (IFNg, Ifit1) in the Type I IFN blockade group." (PMID 40260261, 2025). "Interestingly, ANXA2-regulated genes were also enriched in inflammatory pathways, including influenza A, herpes simplex infection, measles, hepatitis C, type I interferon-mediated signaling pathway, cytokine-mediated signaling pathway, and interferon-gamma- mediated signaling pathway." (PMID 35906541, 2022). "An additional complexity is that both endogenous and administered IFNs may interact in an additive, synergetic or cross‐inhibitory manner, as demonstrated for the interplay between IFNα and IFNγ and the intricate relationship between IFNα and IFNλ in hepatitis C." (PMID 27520969, 2016). "Importantly, CD may present for the first time during treatment of hepatitis C infection, as ribavirin and interferon Alfa enhance type 1 T helper cell immune responses and increase interferon gamma gene expression." (PMID 24348636, 2013).
periodontal disease (40 papers, 2013 to 2025). "Investigating the impact of rs2430561 in IFNγ on comorbidity using binary logistic regression analyses, the A allele was confirmed as an independent risk factor for severe periodontal disease and RA (p = 0.024)." (PMID 30890897, 2019). "A mouse model of alveolar bone loss induced by periodontopathic bacteria Porphyromonas gingivalis showed that CD4+ T cell-derived IFNγ and IL-6 were important effectors of bone loss associated with periodontal disease." (PMID 30158833, 2018). "Specifically, the reduction in TNFα was significant only in the gingivitis subgroup (p = 0.02), while IFNγ showed a consistent and highly significant decrease across all stages of periodontal disease (p < 0.0001 for all comparisons)." (PMID 41280935, 2025). "IFNgama(γ), known as type II interferon, has more powerful effects on immune system modulation and studies related to periodontal diseases have evaluated IFNγ much more than IFNα." (PMID 38691206, 2024). "IFNg has an essential role as a proinflammatory agent, which influences the initiation and progression of periodontal disease." (PMID 34784626, 2022). "During chronic inflammation from diseases, such as periodontal disease, the proinflammatory cytokines interferon-gamma (IFNγ) and tumor necrosis factor-α (TNFα) alter bone remodeling." (PMID 30158833, 2018). "Interferon gamma (IFN-γ), whose gingival cervical fluid level is considered to be related to the severity of periodontal disease, is a further signature inflammatory cytokine appearing during the periodontal destructive process." (PMID 29250118, 2017). "High levels of IL-1β, and IFNγ, which play key roles in inflammatory immune responses, have been identified in periodontal disease." (PMID 28962660, 2017). "Our study suggests that polymorphisms in the IL-4 gene not only affect the production of the IL-4 cytokine but can influence production of several other cytokines, such as IL-10, IFNγ, IL-1β, IL-6, and TNFα, which in turn can affect periodontal disease." (PMID 25530681, 2014). "In a multivariate risk model, higher age, male gender, smoking, and the higher incidence of P.g. but not the A allele of IFNγ SNP rs240561 had predictive value for severe periodontal disease." (PMID 30890897, 2019). "It should be emphasized that inflammatory cytokines, such as interferon-gamma (IFN-γ) and TNF-α, which are elevated in periodontal disease, can activate IDO, the rate-limiting enzyme of the KP, supporting the link between the oral microbiome and the KP." (PMID 39590344, 2024). "Interferon gamma (IFN-γ) is also an immunoregulatory cytokine that plays an important role in the activation of inflammatory processes, which are the basis of periodontal disease." (PMID 36830992, 2023). "Although, interferon gamma and tumor necrosis factor family members have been implicated in such models, the secretoglobin gene super family cytokine has not been highlighted previously in any models of periodontal disease or inflammation; thus, warranting further study." (PMID 32157085, 2020). "Interferon gamma (IFN-γ) is an immunoregulatory cytokine that, when activated by its receptor, plays an important role in the activation of inflammatory processes, which are the basis of periodontal disease." (PMID 29966238, 2018).